BDNF (brain derived neurotrophic factor)
Diseases named in the same sentence as BDNF in open-access papers (continued):
Sharing a sentence is not in itself a finding about the gene and the disease.
Alzheimer disease (continued). "Although persons with Alzheimer’s disease have lower cortical levels of BDNF, evidence regarding the association between circulating BDNF and cognitive function is conflicting." (PMID 24670553, 2014). "Cross-sectional genetic association studies have reported equivocal results on the relationship between the brain-derived neurotrophic factor (BDNF) Val66Met and risk of Alzheimer’s disease (AD)." (PMID 24475133, 2014). "In patients with early Alzheimer’s disease, up-regulation of BDNF with lithium treatment has been associated with increases in cognitive performance." (PMID 23320462, 2013). "Brain- derived neurotrophic factor (BDNF) is linked to neurodegenerative diseases (e.g. Alzheimer disease and Parkinson disease) which are often characterized by olfactory impairment." (PMID 23924085, 2013). "Another study found an association between a SNP in the BDNF gene (C270T), a SNP that has been associated with late-onset AD in some but not all studies, and executive function in patients with Alzheimer’s disease." (PMID 24086677, 2013). "BDNF has been associated with neural stem cell-induced benefits in transgenic model of Alzheimer disease and has a critical role in recovery after ischemic stroke." (PMID 23717557, 2013). "We addressed the role of BDNF in Alzheimer’s disease (AD) by investigating behavior and neurochemistry in double mutant mice generated by crossing BDNF-deficient (Bdnf+/−) mice with an AD mouse model, APdE9 mice." (PMID 23844236, 2013). "BDNF, whose deficiency is associated with a number of neurodegenerative disorders (e.g. Huntington’s disease, Alzheimer’s disease, and Parkinson’s disease), is also downregulated in the diabetic retina." (PMID 22211688, 2012). "With trafficking abnormalities implicated in Alzheimer's disease, Huntington's disease, and others, the ability to image BDNF with temporal and spatial resolution is critical." (PMID 22720171, 2012). "The neurotrophins NGF and BDNF are associated with the early changes seen in MCI leading on to Alzheimer’s disease." (PMID 22654716, 2011). "Reduced BDNF levels lead to a higher susceptibility of neurons to cell death in several neurodegenerative diseases including HD and Alzheimer's disease." (PMID 20507609, 2010). "Association between BDNF Val66Met polymorphism and Alzheimer disease, dementia with Lewy bodies, and Pick disease." (PMID 21034472, 2010). "Neurodegenerative diseases, including Alzheimer’s disease and Parkinson disease, have been associated with reduced BDNF expression." (PMID 19270793, 2009). "In addition to microbiome-induced inflammation, alterations in brain-derived neurotrophic factor (BDNF) signaling have been implicated in the pathophysiology of Alzheimer’s disease and other neurodegenerative conditions." (PMID 40880682, 2025). "In summary, induction of BDNF constitutes a pivotal mechanism underlying curcumin’s neuroprotective actions, reinforcing its therapeutic potential as an adjunctive or preventive strategy in Alzheimer’s disease, Parkinson’s disease, and other CNS disorders." (PMID 40944272, 2025). "Alzheimer's disease is associated with BDNF deficiency, which causes neuronal degeneration." (PMID 38524067, 2024). "Notably, decreased BDNF levels are associated with neuronal loss in several neurodegenerative diseases, including Parkinson's disease, Alzheimer's disease, multiple sclerosis, and Huntington's disease." (PMID 38617040, 2024). "Low BDNF levels detected during early-stage in Parkinson's disease (PD), Huntington's disease (HD), Alzheimer’s Disease (AD), and multiple sclerosis (MS) may be associated with underlying pathogenic mechanisms." (PMID 37287291, 2024). "BDNF depletion is associated with neuroinflammation and neuronal apoptosis in Alzheimer’s disease." (PMID 38721616, 2024).
Alzheimer disease (continued). "Research conducted on humans indicates that variations of levels of BDNF in the peripheral bloodstream are positively linked to hippocampus size and cognition, having a pivotal role in diseases such as Alzheimer’s disease, Parkinson’s disease, and Huntington’s disease." (PMID 37631295, 2023). "Understanding the molecularmechanisms underlying the regulation of BDNF by tPA/plasmin may providenew insights into the pathogenesis of Alzheimer’s disease andidentify new potential therapeutic targets." (PMID 37810633, 2023). "The additional effects of omega-3 FAs may reduce the production of amyloid-β, implicated in Alzheimer’s disease, and increase brain-derived neurotrophic factor (BDNF) and synaptic protection." (PMID 37759879, 2023). "In addition, women and the elderly are also high‐risk groups of Alzheimer's disease and other diseases related to abnormal BDNF levels." (PMID 35274832, 2022). "The deprivation of neurotrophic effect of BDNF has been involved in an increased inflammatory cytokines release and the neurodegeneration associated with Alzheimer disease, while the protective effect of the physical exercise on memory loss has been related to an increased BDNF production." (PMID 35344113, 2022). "None of the participants suffered from endocrine conditions with altered cortisol production (Cushing syndrome or Addison's disease) or from neurodegenerative diseases associated with changes in cortisol and BDNF levels like Alzheimer's disease, Parkinson's disease, or Huntington's disease." (PMID 35250657, 2022). "In addition, decreased BDNF levels/signaling have been implicated in neurodegenerative disorders including Alzheimer’s disease (AD), Parkinson’s disease (PD), and Huntington’s disease (HD)." (PMID 35887357, 2022). "Thus, 7,8-DHF has the same neurotrophic properties as BDNF and was proposed as useful for treating various BDNF-implicated human disorders including Alzheimer’s disease." (PMID 33377988, 2021). "Several lines of evidence suggest that lower BDNF content could be associated with Alzheimer’s disease pathogenesis." (PMID 34017238, 2021). "BDNF in these fluids has been studied in several neurodegenerative diseases: patients with Parkinson’s and Alzheimer’s disease (AD) have reduced serum BDNF levels, and restoration of BDNF may ameliorate behavioural deficits and neuronal loss in AD models." (PMID 33568689, 2021). "Furthermore, lower levels of BDNF in cerebrospinal fluids are associated with the progression of mild cognitive impairment to Alzheimer’s disease." (PMID 32894176, 2020). "This also becomes clear in the context of multiple neurodegenerative disorders, where a single nucleotide polymorphism (SNP) in the BDNF gene is associated to increased susceptibility, incidence and severity of MS and Alzheimer’s disease (AD), correlating with cognitive dysfunction." (PMID 33117368, 2020). "BDNF/TrkB neurotrophic signaling regulates neuronal development, differentiation, and survival, and deficient BDNF/TrkB activity underlies neurodegeneration in Alzheimer’s disease (AD)." (PMID 31315045, 2019). "Alzheimer’s disease (AD) progression has also been associated with impaired reconsolidation and reduced BDNF signaling, suggesting that increasing BDNF function during reconsolidation could partially counteract declarative memory deficits in AD patients." (PMID 31507380, 2019). "Meanwhile, some other pathological proteins in Alzheimer's disease such as amyloid precursor protein, presenilin, phosphorylated tau protein, and brain-derived neurotrophic factor are associated with Aβ deposition and contribute to the regulation of neuronal function in Alzheimer's disease." (PMID 28377692, 2017). "Moreover, reduced function of BDNF is implicated in Alzheimer′s disease and a host of neurodevelopmental and learning disorders while elevated expression is a marker for high cognitive function in aging." (PMID 28208656, 2017).
Alzheimer disease (continued). "Investigation of disease-related changes in BDNF transport might provide insights into the cellular mechanism underlying, for example, Alzheimer's disease (AD)." (PMID 26881108, 2016). "This latter interaction between the Met allele and high beta amyloid load (a risk factor of Alzheimer's disease) suggests that the polymorphism, hence BDNF, might have an effect on disease progression." (PMID 24760076, 2014). "In humans, BDNF levels are lower in AD patients than controls in the hippocampus and cortical regions associated with AD; in the healthy adult mouse, BDNF levels are high in brain regions associated with Alzheimer’s disease (AD)." (PMID 24670553, 2014). "Our goal was to test whether BDNF single nucleotide polymorphisms (SNPs) impact Alzheimer’s Disease-related brain imaging and cognitive markers of disease." (PMID 24086677, 2013). "A neurotrophic factor starvation, including NGF and BDNF deficiency, that begins in the early stages of Alzheimer disease (AD) and ultimately causes neuronal degeneration, cell death, and loss of cholinergic neurotransmission in the late stages of the disease has been reported." (PMID 23320097, 2013). "Alzheimer’s disease brains are deficient in brain-derived neurotrophic factor (BDNF), a key regulator of synaptic plasticity and memory, and of major significance is the recent finding that miRNA-dependent dysregulation of BDNF participates in the pathogenesis of Alzheimer’s." (PMID 23503168, 2013). "Moreover, both oestrogen depletion and low serum BDNF levels have been identified as risk factors for Alzheimer's disease." (PMID 21247257, 2012). "In Alzheimer’s disease, the cognitive dysfunction is exacerbated by deficient reconsolidation, in which case the TrkB agonist or small molecules for the induction of BDNF expression might be effective to enhance memory and cognitive function." (PMID 23185492, 2012). "The loss of BDNF, considering its importance in synaptic plasticity, may explain the reduction in synapses seen in early stage Alzheimer’s disease." (PMID 22654716, 2011). "Furthermore, neurobiological mechanisms are implicated in other neurodegenerative conditions, including Alzheimer’s disease and aging, where exercise-induced myokine signaling and BDNF regulation promote neuroprotection, suggesting shared mechanisms involved in healthy aging and neuroprotection." (PMID 41515929, 2025). "In Alzheimer’s Disease (AD), for instance, reduced BDNF levels are associated with the accumulation of beta-amyloid plaques and tau tangles, while in Parkinson’s disease, BDNF stimulation can promote the dopaminergic neuron survival and differentiation in the substantia nigra." (PMID 38645426, 2024). "Furthermore, BDNF is linked to genetic networks related to brain aging and Alzheimer’s disease." (PMID 39935805, 2024). "In addition, the association between late-onset Alzheimer’s disease and the C270T polymorphism in the BDNF gene and the association between the increased risk of suicide attempts in depressed patients and polymorphism of TrkB and p75NTR receptors have been described." (PMID 36831706, 2023). "Also, the BDNF-Met allele is associated with increased levels of biomarkers such as tau and phospho-tau and poorer cognitive performance in non-symptomatic as well as in symptomatic dominantly inherited Alzheimer’s disease." (PMID 37446337, 2023). "Because neuronal BDNF plays an important role in long-term potentiation, synaptic plasticity, and neurogenesis, reduced BDNF expression is associated with neuronal diseases such as bipolar disorder, Huntington’s disease, Alzheimer’s disease, and Parkinson’s disease." (PMID 36101441, 2022). "While BDNF has been consistently associated with better cognitive performances in healthy individuals and was found to be a protective factor against memory impairment in neurodegenerative disorders (such as Alzheimer disease), its role in neuroinflammatory diseases is still poorly understood." (PMID 33815257, 2021).
Alzheimer disease (continued). "Since synaptic dysfunction is evidence of neurodegenerative diseases, such as Parkinson’s disease, Alzheimer’s disease, and Huntington’s disease, promoting the expression of BDNF to repair the synaptic loss could be a strategy for attenuating neurodegenerative disorders." (PMID 33809381, 2021). "Previous research has demonstrated that pro‐BDNF could cause neuronal apoptosis by inducing p75NTR pathogenicity and a decrease of trophic effects in patients with Alzheimer's disease, suggesting that pro‐BDNF neurotoxic signaling is associated with stimulation of p75NTR ICD." (PMID 33377633, 2020). "The benefit of PTZ on memory and neuronal plasticity together with its potential neuroprotective effect via BDNF may also argue in favor of considering GABAA antagonist therapy for neurological disorders associating memory deficit to neurodegeneration such as Alzheimer’s disease." (PMID 26743578, 2016). "Previous researches also indicated acupuncture at this acupoint improves cognitive function of APP/PS1 Alzheimer’s disease mice, modulates the brain-derived neurotrophic factor secretion in the hippocampal dentate gyrus." (PMID 41530867, 2026). "Deficits in BDNF/TrkB signalling and trafficking have been identified in several neurodegenerative diseases, including Alzheimer's disease (AD)." (PMID 41667435, 2026). "This table summarizes key studies on BDNF gene therapy in Alzheimer’s disease models, highlighting the delivery methods, primary findings, and major limitations." (PMID 40656325, 2025). "A neuroprotective effect for the estrogen regulation of BDNF is consistently seen in individuals with various pathological conditions such as stress, hypertension, ischemic brain injury, and Parkinson’s and Alzheimer’s diseases." (PMID 40141172, 2025). "Recent studies highlight its potential neuroprotective role in neurodegenerative diseases like Parkinson’s and Alzheimer’s disease by reducing CNS oxidative stress, increasing blood flow, and upregulating BDNF expression." (PMID 41154611, 2025). "Physical exercise has been shown to protect against cognitive decline in Alzheimer's disease (AD), likely through the upregulation of brain‐derived neurotrophic factor (BDNF)." (PMID 39957598, 2025). "Hypoxia induced hippocampal neurogenesis in adult rats modeling depression and elicited the cerebrocortical expression of erythropoietin and brain-derived neurotrophic factor in transgenic mice modeling Alzheimer’s disease." (PMID 41301754, 2025). "For example, empirical evidence suggests that the reduction of BDNF levels in Alzheimer's disease is significantly correlated with amyloid accumulation, tau hyperphosphorylation, and neuronal apoptosis." (PMID 39744428, 2025). "Specifically, TMS targeting the prefrontal cortex and hippocampal networks improves cholinergic signaling and boosts brain-derived neurotrophic factor (BDNF) levels, as observed in the 3xTgAD mouse model of Alzheimer's disease." (PMID 40438568, 2025). "BDNF has proven more effective than NGF in restoring neural circuits, reducing neuronal loss, and improving brain function in Alzheimer’s disease." (PMID 40869138, 2025). "In a high-risk Alzheimer's disease (AD) mice model, a 3-month TRE (18 h fasting per day) enhanced brain-derived neurotrophic factor signaling, thus constituting one mechanism through which fasting interventions ameliorate cognitive decline." (PMID 41536827, 2025). "The relationship between HDACs, BDNF, and neurodegenerative diseases such as Alzheimer’s disease (AD) is also significant." (PMID 40867911, 2025). "This study employed a specific agonist of the BDNF receptor TrkB to elucidate the mechanism by which lidocaine influences BDNF, leading to Alzheimer's disease‐like pathology and cognitive decline." (PMID 41318982, 2025). "Although this study was conducted in the context of Alzheimer's disease, the examined pathways, such as BDNF upregulation and synaptic plasticity, are also disrupted in PD." (PMID 40735395, 2025).
Alzheimer disease (continued). "This indirect link among orexin secretion, BDNF production and neurodegeneration makes orexin as a relevant target to be addressed in the management of disorders such as Parkinson’s and Alzheimer’s diseases; we will discuss this point further." (PMID 41009546, 2025). "Recent studies have underscored the significant role of astrocytes and brain-derived neurotrophic factor (BDNF) in the development of Alzheimer's disease (AD)." (PMID 40016145, 2025). "This preservation occurs through BDNF-mediated activation of the AMPK/PINK1/Parkin pathway in Alzheimer’s disease models." (PMID 40035032, 2025). "For example, the study that demonstrated SF’s effect on neural plasticity using the triple-transgenic mouse model of Alzheimer’s disease, showed that SF regulated BDNF expression specifically via HDAC inhibition." (PMID 40284217, 2025). "Our previous study also found that aerobic exercise elevated hippocampal and cortical BDNF levels in patients with progressive neurodegenerative diseases, such as Alzheimer’s disease (AD)." (PMID 40867124, 2025). "In the context of Parkinson’s and Alzheimer’s diseases, physical exercise has been shown to significantly increase BDNF expression, especially in the hippocampus, a region directly associated with memory and learning." (PMID 40566596, 2025). "Increased BDNF levels and BDNF-mediated hippocampal neurogenesis prevent memory deficits in Alzheimer’s disease mouse models." (PMID 40715999, 2025). "Activation of ERK and CREB by phosphorylation leads to increased BDNF expression and exerts neuroprotective effects in Alzheimer's disease (AD)." (PMID 39609371, 2025). "BDNF supports hippocampal neurogenesis, synaptic plasticity, and the maintenance of dendritic complexity—processes that are compromised in aging and Alzheimer’s disease." (PMID 41283454, 2025). "Dopamine released in the brain is involved in reward system mechanisms and feelings of well-being, and is also related to levels of brain-derived neurotrophic factor (BDNF), which is associated with the development of Alzheimer’s disease." (PMID 39995889, 2025). "In a study, elderly individuals with higher peripheral BDNF levels showed reduced chances of developing Alzheimer’s disease." (PMID 40407530, 2025). "Reduced levels of BDNF have been observed in neurodegenerative diseases, including PD and Alzheimer’s disease (AD)." (PMID 40309866, 2025). "Its neuroprotective effects include the regulation of amyloid precursor protein processing and the support of BDNF signaling—both of which are vital to the pathogenesis of Alzheimer’s disease." (PMID 40867144, 2025). "In Alzheimer’s disease rats, BDNF was found to positively regulate the secretion of FNDC5 by muscle cells, thereby improving cognitive function in these rats." (PMID 41195080, 2025). "This study identifies distinct metabolic (octadecanedicarboxylic acid, prolinamide, leucine, ascorbic acid) and biomarker profiles (phosphorylated tau217, 8-hydroxy-2′-deoxyguanosine, brain-derived neurotrophic factor) in Alzheimer’s disease." (PMID 41229615, 2025). "This Irisin–BDNF interaction is particularly significant in the context of neurodegenerative diseases such as Alzheimer’s disease (AD) and Parkinson’s disease (PD)." (PMID 40001564, 2025). "A previous study revealed that ASP markedly upregulated the expression level of BDNF and its specific receptor tropomyosin‐related kinase B in Alzheimer's disease rats." (PMID 41019183, 2025). "Reduced levels of neurotrophic factors (e.g., BDNF) were described in neurodegenerative disorders, such as Parkinson’s disease, Alzheimer’s disease, and multiple sclerosis." (PMID 40407530, 2025). "In fact, in the context of Alzheimer’s disease (AD), research is focusing on BDNF as a potential treatment and protective factor against neurodegeneration." (PMID 41009546, 2025).